TRPC4AP (transient receptor potential cation channel subfamily C member 4 associated protein)
Description:
Substrate-recognition component of a DCX (DDB1-CUL4-X-box) E3 ubiquitin-protein ligase complex required for cell cycle control. The DCX(TRPC4AP) complex specifically mediates the polyubiquitination and subsequent degradation of MYC as part of the DesCEND (destruction via C-end degrons) pathway. The DesCEND (destruction via C-end degrons) pathway recognizes a C-degron located at the extreme C terminus of target proteins, leading to their ubiquitination and degradation. The DCX(TRPC4AP) complex specifically recognizes proteins with an arginine at the minus 3 position (R-3 motif) at the C-terminus, such as MYC, leading to their ubiquitination and degradation. Also participates in the activation of NFKB1 in response to ligation of TNFRSF1A, possibly by linking TNFRSF1A to the IKK signalosome (By similarity). Involved in JNK activation via its interaction with TRAF2 (By similarity). Also involved in elevation of endoplasmic reticulum Ca(2+) storage reduction in response to CHRM1 (By similarity).
Synonyms: C20orf188; TRRP4AP; DKFZP727M231; DKFZp586C1223; dJ756N5.2; PPP1R158; TRUSS
Tractability: Antibody: its Gene Ontology location is reachable by antibodies, with high confidence. PROTAC: UniProt records ubiquitination sites on it; ubiquitination databases record sites on it.
Gene: Protein-coding gene on chromosome 20 (34,995,209 to 35,092,868, reverse strand). Ensembl gene ENSG00000100991.
Subcellular location: Cytoplasm, perinuclear region
Subcellular location (Human Protein Atlas): Cytosol
Pathways (Reactome):
Transport of small molecules: TRP channels
Gene Ontology:
Molecular function: phosphatase binding; protein binding; ubiquitin-like ligase-substrate adaptor activity; calcium channel activity
Biological process: protein ubiquitination; ubiquitin-dependent protein catabolic process; ubiquitin-dependent protein catabolic process via the C-end degron rule pathway; calcium ion transmembrane transport
Cellular component: Cul4-RING E3 ubiquitin ligase complex; Cul4A-RING E3 ubiquitin ligase complex; cytosol; plasma membrane; perinuclear region of cytoplasm
Genetic constraint (gnomAD): Loss-of-function variants: 41 observed, 94.25 expected, observed/expected ratio (o/e) 0.44, 90% interval 0.34 to 0.56. The upper end of that interval is the gene's LOEUF score, 0.56, which puts it in group 2 of 6, group 1 being the genes least tolerant of losing a copy. Missense variants: 839 observed, 978.68 expected, observed/expected ratio (o/e) 0.86, 90% interval 0.81 to 0.91. Synonymous variants: 398 observed, 387.36 expected, observed/expected ratio (o/e) 1.03, 90% interval 0.95 to 1.12.
Homologues: Orthologues: chimpanzee TRPC4AP (99% identical), dog TRPC4AP (99% identical), pig TRPC4AP (99% identical), guinea pig TRPC4AP (98% identical), rat Trpc4ap (98% identical), mouse Trpc4ap (98% identical), macaque TRPC4AP (95% identical), rabbit TRPC4AP (93% identical), tropical clawed frog trpc4ap (78% identical), zebrafish trpc4apa (72% identical), zebrafish trpc4apb (59% identical).
Diseases named in the same sentence as TRPC4AP in open-access papers:
TRPC4AP is named in the same sentence as 7 diseases in open-access papers, as found by Europe PMC text mining. Sharing a sentence is not in itself a finding about the gene and the disease. The quoted sentences say what the papers report.
breast cancer (2 papers, 2017 to 2025). A primary or metastatic malignant neoplasm involving the breast. "No direct association was observed between TRPC4AP and NUDT12 and mammary tumors." (PMID 40839607, 2025).
Primary hypothyroidism (2 papers, 2021). A type of hypothyroidism that results from a defect in the thyroid gland. "Recently, a transient receptor potential channel 4-associated protein (TRPC4AP, also known as TNFα-receptor ubiquitous signaling and scaffolding protein, TRUSS) was suggested to be an important gene causing congenital primary hypothyroidism." (PMID 33919125, 2021).
Alzheimer disease (1 paper, 2021). A progressive, neurodegenerative disease characterized by loss of function and death of nerve cells in several areas of the brain leading to loss of cognitive function such as memory and language. "Among them, the protein encoded by TRPC4AP gene is believed to be able to interact with TRPC ion channel and promote calcium release into cells, which is found to be related to Alzheimer's disease." (PMID 34512754, 2021).
glioma (1 paper, 2024). A benign or malignant brain and spinal cord tumor that arises from glial cells (astrocytes, oligodendrocytes, ependymal cells). "Notably, this drug promotes Pyk2 upregulation, hinders glioma progression and enhances focal adhesion formation by inhibiting TRPC4AP." (PMID 38784033, 2024).
tumor (5 papers, 2012 to 2025). "The high-CMLHMS group exhibited upregulation of genes such as TRPC4AP, NUSAP1, EFNA1, KMT2A, and NCOA6, which are implicated in chromatin remodeling, cell proliferation, and tumor progression." (PMID 40144021, 2025). "A single-cell study of gene expression in the tumor microenvironment, encompassing immune cells, stromal cells, malignant cells, and functional cells, revealed that the key gene in the model was TRPC4AP, which was more widely distributed in malignant cells." (PMID 38784033, 2024). "The CNV of TRPC4AP was positively correlated with its mRNA level in 27 of 33 tumour types." (PMID 35493463, 2022).
cancer (2 papers, 2019 to 2021). A tumor composed of atypical neoplastic, often pleomorphic cells that invade other tissues. "The results of high-throughput sequencing showed that TRP ion channel-related genes, such as TRPC7-AS1, TRPC4AP, PKD1P6, and PKD1P1, were highly expressed in cancer tissues than those in paracancerous tissues." (PMID 34512754, 2021). "We also found that the expression of TRP ion channel-related genes such as TRPC7-AS1, TRPC4AP, PKD1P6, and PKD1P1 in cancer tissues was higher than those in adjacent tissues." (PMID 34512754, 2021).
TRPC4AP also shares sentences with these, for which no sentence is quoted: type 2 diabetes (1 paper).